NR4A2 (nuclear receptor subfamily 4 group A member 2)
Diseases named in the same sentence as NR4A2 in open-access papers (continued):
Sharing a sentence is not in itself a finding about the gene and the disease.
Intellectual disability (10 papers, 2015 to 2025). "All the patients with pathogenic or likely pathogenic variants in NR4A2 show developmetal delay and/or intellectual disability." (PMID 38791237, 2024). "Here, we reported two novel variants occurring de novo in NR4A2, c.1541-2A > C and c.915C > A (p.Cys305*), in two patients presenting with mild intellectual disability, language impairment, and attention deficit disorder." (PMID 35992907, 2022). "Finally, Nuclear Receptor Subfamily 4 Group A Member 2 (NR4A2) is associated with intellectual disability and ASD." (PMID 34207213, 2021). "Here we report two pediatric NR4A2-related cases presenting with global developmental delay, speech impairment, and intellectual disability." (PMID 41019763, 2025). "In some reports, the deletion affected Nr4a2 and GPD2 genes and caused intellectual disability and language impairment." (PMID 34880728, 2021). "In recent years, much attention has been directed to Nr4a2 function in hippocampal synaptic plasticity, learning, and memory, addressing much interest to the role of Nr4a2 in brain pathologies that course with cognitive or intellectual disabilities." (PMID 34880728, 2021). "The presence of Nr4a2 deletions in patients with autism spectrum disorder has also related Nr4a2 with intellectual disability." (PMID 34880728, 2021).
autoimmune disease (9 papers, 2013 to 2022). A disorder resulting from loss of function or tissue destruction of an organ or multiple organs, arising from humoral or cellular immune responses of the individual to their own tissue constituents. "Using RNA interference treatment and generating transgenic Nr4a2 cKO mice with a T‐cell‐specific Nr4a2 deficiency, we reported that NR4A2 was required for Th17 cell secretion of IL‐21, which in turn promoted autoimmune disease." (PMID 36069030, 2022). "Our previous studies have associated the expression of Nr4a2 with autoreactive Th cells in patients with the autoimmune disease multiple sclerosis and its mouse model." (PMID 36069030, 2022). "Overall, it appears that intrinsically self‐reactive Th cells in systemic autoimmune disease may have shared phenotypes with Treg cells, with NRP1+ conventional Th cells highly associated with autoimmune disease induction in NR4A2‐dependent manner." (PMID 36069030, 2022). "In addition, the ability to regulate PRL levels with selective NR4A2 antagonists may provide novel approaches to manage hyperprolactinemia associated with other autoimmune disorders and conditions." (PMID 25717285, 2015). "As a consequence suppressing NR4A1 expression promotes autoimmunity while deletion of NR4A2 protects from Th17-mediated autoimmune diseases." (PMID 33597928, 2020). "Further, we reveal a critical involvement of NR4A2 in Th17 cell functions and Th17 cell-driven autoimmune diseases." (PMID 23437182, 2013). "The Nr4a orphan nuclear receptors, Nr4a1 (Nur77), Nr4a2 (Nurr1), and Nr4a3 (Nor1), are early‐immediate response genes that can be induced by a variety of physiological stimuli such as inflammation during experimental autoimmune disease models." (PMID 34358410, 2021). "Furthermore, knocking out Nr4a2 in mice can trigger an abnormal activation of Th2 cells and a Th2-type autoimmune response, leading to the development of systemic multiorgan autoimmune diseases." (PMID 29541411, 2018). "Thus, NR4A2 appears to control Th17 differentiation and so plays an essential role in the development of Th17-mediated autoimmune disease." (PMID 23437182, 2013). "As NR4A2 is also upregulated during human autoimmune disease, targeting NR4A2 may provide a new therapeutic approach in treating autoimmune disease." (PMID 23437182, 2013). "Based on these findings, we propose that NR4A2 has direct effects on T cell pathogenicity or plays a critical role in continuous new Th17 differentiation and thus it orchestrates effector functions of Th17 cells in mediating autoimmune diseases." (PMID 23437182, 2013). "Together, these findings identify Nr4a2 as a fundamental component in the regulation of T helper cell differentiation and development, namely, a positive regulation of Tregs and a negative regulation of Th2 cells, demonstrating its crucial roles in autoimmune diseases." (PMID 29541411, 2018). "Furthermore, our discovery of the key role of NR4A2 signalling in Th17 differentiation and our identification of the involvement of NR4A2 in generating autoimmune response in vivo suggest a new target for intervention in Th17-mediated autoimmune disease." (PMID 23437182, 2013). "Thus, future therapies targeting NR4A2 may prove highly effective in treating particular autoimmune diseases." (PMID 23437182, 2013). "Recent research demonstrates that Nr4a2 participates in the differentiation of CD4+ T cells and plays an important role in autoimmune diseases." (PMID 29541411, 2018). "Here we tested whether or not NR4A2 overexpression is common to T cells involved in autoimmune diseases." (PMID 23437182, 2013).
colon cancer (9 papers, 2013 to 2025). "In colon cancer, the overexpression of NR4A2 is associated with increased chemoresistance and serves as a negative prognostic indicator." (PMID 40361912, 2025). "Limited data suggest that, like NR4A1, NR4A2 is also a pro-oncogenic factor in solid tumors, and in colon cancer, NR4A2 overexpression predicts an unfavorable prognosis and chemoresistance." (PMID 40332813, 2025). "This markedly elevates the mRNA levels of NR4A2, COX2, and the regulatory proteins AREG and IL-6, thereby facilitating the development of sporadic or colitis-associated colon cancer." (PMID 39683442, 2024). "The effects of DIM-3,5-Br2, DIM-3-CI-5-CF3 and DIM-3,5-CI2 on NR4A1- and NR4A2-dependent transactivation were determined in RKO, SW480 and HCT116 colon cancer cell lines transfected with GAL4-NR4A1 or GAL4-NR4A2 chimeras and UAS-Luc, which contains five yeast GAL4 response elements." (PMID 40332813, 2025). "The results of NR4A2 knockdown in colon cancer cells confirmed the pro-oncogenic activity of this gene and was similar to that previously observed for NR4A2 other cancer cell lines and consistent with the unfavorable prognosis for colon cancer patients that overexpress NR4A2." (PMID 40332813, 2025). "Thus, TORC1 activation might be an important molecular mechanism mediating the effects of PGE2 on colon tumor growth, inducing pro‐tumorigenic transcription of genes including NR4A2, COX2, AREG, and IL‐6." (PMID 35920319, 2023).
colorectal cancer (9 papers, 2013 to 2025). A primary or metastatic malignant neoplasm that affects the colon or rectum. "Further studies demonstrated that NR4A2 could modulate fatty acid oxidation pathways in colorectal cancer." (PMID 35965537, 2022). "Many transcription factors involved in resistance to CDDP have been differentially expressed in this study, such as NRA42 (Nuclear Receptor subfamily 4 group A member 2; P<0.001), an orphan nuclear receptor that confers chemoresistance in GC and colorectal cancer." (PMID 31990955, 2020). "For example, high NR4A2 expression predicted poor prognosis and promoted chemo-resistance in squamous cell carcinoma (SCC) and colorectal cancer." (PMID 32368184, 2020). "Additionally, the effect of mature miR-34 mimics on NR4A2 expression was assessed in another colorectal cancer cell line, RKO, with similar results observed on CDKN1A and NR4A2 expression." (PMID 27121375, 2016). "However, the mechanisms elucidated in this study indicated that NR4A2 was important for PGE2-mediated regulation of apoptosis, and thus is likely to mirror mechanisms such as inflammatory signaling pathways, which are known to play a prominent role in colorectal cancer." (PMID 24086717, 2013).
rheumatoid arthritis (9 papers, 2005 to 2022). A chronic, systemic autoimmune disorder characterized by inflammation in the synovial membranes and articular surfaces. "NR4A2 is overexpressed in synovium and cartilage from individuals with rheumatoid arthritis (RA), psoriatic arthritis, and osteoarthritis." (PMID 35529439, 2022). "In addition, NR4A2 is also up-regulated by the upstream molecule TNFα in synovial tissue, contributing to cartilage destruction and ultimately rheumatoid arthritis." (PMID 36093144, 2022). "NR4A2 is over-expressed in inflamed synovial tissues and cartilage from patients with rheumatoid arthritis (RA), osteoarthritis (OA), and psoriatic arthritis (PsA), and NR4A2 is the most highly expressed member of the NR4A receptor family in these tissues." (PMID 25717285, 2015).
autism (8 papers, 2020 to 2026). Persistent deficits in social interaction and communication and interaction as well as a markedly restricted repertoire of activity and interest as well as repetitive patterns of behavior. "Considering that the alteration of cell-autonomous dopaminergic functions is the core hallmark of ASD pathophysiology, NR4A2 mutations have been associated with various disorders related to dopaminergic dysfunction, which contributes to several behavioral manifestations of autism." (PMID 40564942, 2025). "Among the most compelling genes were NR4A2 and HNRNPU, listed as ‘high confidence’ autism-associated genes in the SFARI database given the multiple separate reports identifying mutations in each of these genes in autistic people." (PMID 41507264, 2026). "In other brain regions, key autism susceptibility genes included FOXP1 (caudate and putamen), MEF2C and SATB2 (cortical plate), and TBR1 and NR4A2 (subplate)." (PMID 41279531, 2025).
cervical cancer (8 papers, 2009 to 2024). A primary or metastatic malignant neoplasm involving the cervix. "NR4A2 upregulation induced cell growth in cervical cancer and activation of Notch signaling silenced NR4A2 to repress cervical cancer progression." (PMID 32368184, 2020). "Our previous study showed the effects of Notch1 on certain genes such as NR4A2, p63 in cervical cancer Hela cells." (PMID 28423575, 2017). "In our previous study, the nuclear receptor gene NR4A2 was found to be involved in Notch-mediated downstream signaling pathways in cervical cancer cells." (PMID 28423575, 2017). "NR4A2 belongs to the steroid nuclear hormone receptor superfamily and has a role in cell transformation in cervical cancer." (PMID 19826427, 2009). "Our previous study also showed that NR4A2 stimulated cervical cancer cell growth." (PMID 28423575, 2017). "We have demonstrated that NR4A2 might act as an oncogene in cervical cancer cells." (PMID 28423575, 2017).
neuroblastoma (8 papers, 2013 to 2025). Neuroblastoma (NB) is the most common solid, extracranial childhood tumor. "In neuroblastoma, a prevalent pediatric malignancy, NURR1 (NR4A2) functions as a critical tumor suppressor." (PMID 40926269, 2025).
Anxiety (7 papers, 2019 to 2025). Intense feelings of nervousness, tension, or panic often arise in response to interpersonal stresses. "Mice lacking Nr4a2 in Car3 ensembles during the embryonic stage or in adulthood display hyperactivity and reduced anxiety-like behaviors." (PMID 40921971, 2025).
bipolar disorder (7 papers, 2010 to 2025). A disorder of the brain that causes unusual shifts in mood, energy, activity levels and the ability to carry out day-to-day tasks. "Probing this interaction between FOS and NR4A2, NESARC shows an Odds Ratio of 5.6 for cocaine abuse among patients with mania in bipolar disorder, relative to the general population." (PMID 21092101, 2010).
experimental autoimmune encephalomyelitis (7 papers, 2013 to 2024). An autoimmune demyelinating disease of the central nervous system that is produced experimentally in animals by the injection of homogenized brain or spinal cord in Freund's adjuvant. "Development of acute experimental autoimmune encephalomyelitis (EAE) depends on Th17 cells expressing the nuclear factor NR4A2." (PMID 26436530, 2015). "Lastly, the Nr4a2 gene-encoding product, nuclear receptor subfamily 4, group A, member 2 (NURR1), is upregulated in MS patients in the pre-disease state and prevents autoimmune neuroinflammation in the experimental autoimmune encephalomyelitis (EAE) model of MS." (PMID 39594496, 2024). "We now demonstrate that such T cells infiltrating the target organ during the induction of experimental autoimmune encephalomyelitis (EAE) and experimental autoimmune uveoretinitis (EAU) specifically express NR4A2." (PMID 23437182, 2013).
ischemia (7 papers, 2018 to 2024). A hypoperfusion of the BLOOD through an organ or tissue caused by a PATHOLOGIC CONSTRICTION or obstruction of its BLOOD VESSELS, or an absence of BLOOD CIRCULATION. "Our data suggested that induction of NR4A2 is an adaptive response to resist cardiomyocyte apoptosis caused by ischemia." (PMID 29531824, 2018). "In the current study, cardiomyocyte apoptosis caused by ischemia was attenuated by NR4A2-enhanced autophagy, suggesting that NR4A2 might be used as a potential therapeutic target for ischemic heart diseases." (PMID 29531824, 2018). "A recent study revealed that NR4A2 was upregulated in mice with ischemia-induced myocardial damage, and the overexpression of NR4A2 would improve myocardial apoptosis." (PMID 36093144, 2022). "For example, NR4A2 knockdown exacerbates cardiomyocyte apoptosis, and upregulation of NR4A2 is regarded as an adaptive response to ischemia-induced cardiomyocyte apoptosis." (PMID 33668039, 2021). "In our research, we found that miR-212-3p expression decreased in ischemia, and its target NR4A2 increased, inhibiting the apoptosis of cardiomyocytes." (PMID 29531824, 2018). "As NR4A2 knockdown aggravates cardiomyocyte apoptosis, while NR4A2 overexpression ameliorates it, NR4A2 upregulation was considered an adaptive response to ischemia-induced cardiomyocyte apoptosis." (PMID 29531824, 2018). "To investigate the possible involvement of NR4A2 in cardiomyocyte apoptosis, we analyzed the changes in NR4A2 in H9c2 cardiomyocytes exposed to ischemia." (PMID 29531824, 2018). "First, NR4A2 was also triggered by serum depletion, which is the same as ischemia-induced autophagy." (PMID 29531824, 2018). "Then, H9c2 cardiomyocytes and neonatal rat cardiomyocytes (NRCMs) exposed to ischemia were both used to detect the effects of NR4A2 knockdown on ischemia-induced cardiomyocyte apoptosis." (PMID 29531824, 2018). "Further study revealed that NR4A2 knockdown could aggravate, while overexpression of NR4A2 could inhibit apoptosis stimulated by ischemia." (PMID 29531824, 2018). "In our study, NR4A2 was upregulated in murine cardiomyocytes exposed to ischemia." (PMID 29531824, 2018).
leukemia (7 papers, 2015 to 2023). A malignant (clonal) hematologic disorder, involving hematopoietic stem cells and characterized by the presence of primitive or atypical myeloid or lymphoid cells in the bone marrow and the blood. "While in solid tumor-derived cell lines, NR4A1 and NR4A2 expression are high, and both receptors exhibit pro-oncogenic activities, in blood-derived tumors (leukemias and lymphomas), NR4A expression, particularly of NR4A1 and NR4A3, is low." (PMID 36831639, 2023). "Some of these genes have been previously found to play important roles in haematopoiesis and leukaemia pathogenesis, e.g. PIM1, BCOR, TNFRSF8 and NR4A2." (PMID 26576536, 2015). "In addition, the anti-metabolite cancer drug, 6-mercaptopurine used to treat leukemia, could induce NR4A2 and NR4A3 through binding to AF-1 domain at the N-terminal of the latter; however, how it induced NR4A2 remains to be further researched." (PMID 33328994, 2020).
melanoma (7 papers, 2013 to 2023). A malignant, usually aggressive tumor composed of atypical, neoplastic melanocytes. "Similarly, the analysis of human melanoma TILs scRNA-Seq data highlighted a correlation of Nr4a1, Nr4a2, and Nr4a3 transcription with inhibitory receptor expression (Pdcd1 and Havcr2)." (PMID 33597928, 2020). "The transcription of Nr4a2 and Nr4a3 was upregulated in CD8+ TILs in an autochthonous melanoma mouse model." (PMID 33597928, 2020). "To achieve this we used a cutaneous melanoma cell line previously found to have low levels of NR4A1 and NR4A2 expression by real time PCR and EMSA." (PMID 24223135, 2013). "For example, NR4A2 was differentially expressed in yr60+ versus yr60- melanoma patients without recurrence." (PMID 33373316, 2020).
atherosclerosis (6 papers, 2012 to 2023). A disease characterized by the build-up of fatty material and calcium deposition in the arterial wall resulting in partial or complete occlusion of the arterial lumen. "NR4A2 is also implicated in the inflammatory response in relation to the development of arthritis, atherosclerosis and psoriasis." (PMID 28301468, 2017). "To expand these observations, we sought to examine the expression profile of NR4A2/3 and MIP-3α expression in vivo in human carotid plaque tissue, given the fact that both genes have been identified as important factors in the pathogenesis of atherosclerosis." (PMID 28167941, 2017).
colitis (6 papers, 2015 to 2024). Inflammation of the colon. "It has been reported that NR4A2-deficient T cells inhibit Foxp3 expression, leading to an abnormal induction of Th1 cells and aggravation of colitis." (PMID 38006062, 2023). "The family member NR4A2 also regulates immune cell function and subsequently colitis, as deletion of NR4A2 in T cells attenuates induction of Tregs and causes aberrant induction of Th1 CD4+ T cells and subsequent exacerbation of colitis." (PMID 31139192, 2019).
epilepsy (6 papers, 2020 to 2024). A brain disorder characterized by episodes of abnormally increased neuronal discharge resulting in transient episodes of sensory or motor neurological dysfunction, or psychic dysfunction. "Pathogenic variants in NR4A2 gene cause a complex neurodevelopmental disorder with special affectation of language, as well as dystonia or other movement disorders, neuropsychiatric disorder and/or epilepsy." (PMID 38791237, 2024). "A recent genetic study with larger cohort identified eight de novo variants of NR4A2 and a deletion containing NR4A2 in nine patients with NDD and epilepsy, further strengthening the association of NR4A2 heterozygous variants with NDD." (PMID 35992907, 2022). "Our study underscores the importance of NR4A2 as a disease gene for neurodevelopmental disorders and epilepsy." (PMID 32366965, 2020). "NR4A2 haploinsufficiency was recently associated with an NDD with language delay and epilepsy." (PMID 36835207, 2023). "Here, we described two novel NR4A2 truncating variants in two unrelated Chinese patients mainly presenting with mild ID/DD, language impairment, and attention deficit, without epilepsy." (PMID 35992907, 2022). "Here we report nine patients with variants in NR4A2 and developmental delay/intellectual disability with or without epilepsy." (PMID 32366965, 2020).
gastric cancer (6 papers, 2013 to 2023). A primary or metastatic malignant neoplasm involving the stomach. "However, NR4A2 has been characterized as a putative tumor suppressor protein in gastric cancer, being down-regulated both in primary gastric cancers and in synchronous liver metastases." (PMID 24086717, 2013).